RHOA (ras homolog family member A)
Diseases named in the same sentence as RHOA in open-access papers (continued):
Sharing a sentence is not in itself a finding about the gene and the disease.
glioma (continued). "Taken together, we have identified a novel RhoA-induced signaling mechanism that enables glioma cells to efficiently invade the white matter of the healthy brain using myelinated nerve fibers as guide structures." (PMID 31062076, 2019). "Lin Yu demonstrated that SND1 (Staphylococcal nuclease domain-containing protein 1) and RhoA were independent predictors of poor prognosis in glioma patients." (PMID 31339860, 2019). "NKCC1 inhibition effectively decreased the activation of Rac1 and RhoA, and the pharmacological inhibition of Rac1 and RhoA dramatically impaired glioma invasion and migration." (PMID 30159893, 2019). "For its parts, in response to a protein complex containing pleiotrophin, secreted by neural precursor from the PVZ, RhoA signaling is activated in glioma cells and induces the migration of glioma cells to the PVZ." (PMID 30333910, 2018). "Major TGF-Beta-EMT inducing factors (RHOA, RAC1, ROCK2, CDC43 and LIMK1) and EMT transcription factors (TWIST1, SOX9, TRIM28 and SERP2) have among the highest risk scores in our glioma transcriptional model." (PMID 28916782, 2017). "Studies from other groups revealed that irradiation can lead to an increased motility of glioma cells and it was argued that this effect is related to the activation of the small GTPases Rac1 and subsequent inhibition of RhoA." (PMID 28926987, 2017). "By now, we found that knockdown of ARHGDIA by siRNA resulted in activating the GTPase activity of Cdc42, Rac1, RhoA, and pAkt to promote glioma cell proliferation and migration." (PMID 27726098, 2016). "Due to the important role of ARHGDIA in the regulation of Rho GTPase, then how does its decreased expression regulate its effector proteins including Rac1/cdc42 and RhoA in glioma cells?" (PMID 27726098, 2016). "Dynamin-related protein 1 (Drp1) was reported to contribute to mitochondrial dynamic regulation and influence glioma cells proliferation and invasion by RHOA/ ROCK1 pathway." (PMID 27852062, 2016). "BDNF infusion reduces M/Mφ infiltration and CD68 immunoreactivity in tumour mass and reduces glioma migration inhibiting the small G protein RhoA through the truncated TrkB.T1 receptor." (PMID 25818172, 2015). "Inhibition of ROCK induces glioma cell migration through Rac1 activation, suggesting that the relative degree of activation between RhoA and Rac1 regulates glioma cell movement." (PMID 24212955, 2011). "Similar to TIMP2, the RHOA gene was also down-regulated in cisplatin-treated glioma cells, and the decreased expression levels were also confirmed through real time PCR analysis." (PMID 21637621, 2010). "Decreased RhoA activity was reported during glioma cell migration." (PMID 33960104, 2022). "Similarly, it has been demonstrated that RhoA and the RhoA-specific GEF Src homology 3 domain-containing guanine nucleotide exchange factor (SGEF) mediate TWEAK-induced cell migration in the glioma cell lines U87 and U118." (PMID 36339601, 2022). "Mechanistic studies further revealed that DRP1 could target RHOA, and thus regulate the proliferation and invasion of glioma cells." (PMID 36192752, 2022). "The authors suggested that Nogo-A may inhibit migration and invasiveness of glioma cells by decreased RhoA-cofilin signalling." (PMID 34601991, 2021). "Mass spectrometry data of the RhoA-induced glioma secretome [Suppl." (PMID 31062076, 2019). "According to recent publications, mediating RhoA associated biological processes, ARHGEF3 has been confirmed to interact with IDH and has unique methylation status in glioma." (PMID 31803734, 2019). "Here, we investigated whether NKCC1 promotes an epithelial–mesenchymal transition (EMT)‐like process in gliomas via the RhoA and Rac1 signaling pathways." (PMID 30159893, 2019). "Additionally, invading glioma cells exhibit an increased Cdc42 and Rac1 activity, but a decreased activity of RhoA at the cell front, held responsible for the enhanced migration of leader cells." (PMID 31003495, 2019).
glioma (continued). "The impact of RhoA and Rac1 on glioma migration is in good agreement with the observation of an increased FAK activation, negatively regulating RhoA and activating Rac1 in glioma, being associated with staging and a poorer prognosis." (PMID 31003495, 2019). "Interestingly, the formin mDia1, which is activated by RhoA, plays a major role in glioma cell polarization." (PMID 31003495, 2019). "Therefore, we suggest that the NKCC1 promotes the EMT‐like process in gliomas via the RhoA and Rac1 signaling pathways." (PMID 30159893, 2019). "The important role of RhoA points to myosin as a further important player in glioma migration." (PMID 31003495, 2019). "Based on our experimental research, we hypothesized that NKCC1 promotes the EMT‐like process in gliomas via the RhoA and Rac1 signaling pathways." (PMID 30159893, 2019). "Therefore, the downregulation of ARHGDIA regulates GTPase activity of Cdc42, Rac1, and RhoA, subsequently, increases Akt phosphorylation and leads to glioma cell proliferation and migration." (PMID 27726098, 2016). "Considered together, our data suggest that the effects of MAZ51 in glioma cells could be mediated through phosphorylation of Akt/GSK3β and activation of RhoA." (PMID 25268128, 2014). "Decreased RhoA activity occurred in correlation with increased glioma cell migration." (PMID 24109588, 2013). "To date, much of the data on RhoA function in glioma remains largely correlative." (PMID 24109588, 2013). "Further analysis revealed that the loss of invasive proteolysis-dependent migration capacity of glioma cells with knockdown of SOX2 could be compensated by a shift to amoeboid migration governed by increased RhoA/ROCK2 signaling." (PMID 22070920, 2011). "Furthermore, CDC42 and RhoA were inversely correlated with miR-185 expression in gliomas." (PMID 25526788, 2014). "Hence, RNAi of SOX2 induces an increased RhoA signaling in U343-MG and U373-MG glioma cells." (PMID 22070920, 2011). "For example, in glioma cells, SHIP2 directly interacts with GTP-bound RhoA, resulting in the promotion of cell polarity and migration." (PMID 38200519, 2024). "In glioma cells, SND1 can induce a long-range chromatin interaction loop between two SND1 recognition positions on the RHOA promoter." (PMID 37885030, 2023). "The results revealed that knockdown of TROAP drastically downregulated the level of MMP2, MMP7, MMP9, RHOA, RHOA, ROCK1 protein in U251 glioma cell lines compared to control group (p < 0.05)." (PMID 34077623, 2021). "Meanwhile, higher levels of RhoA, another ceRNA member of CDKN2B and a downstream factor in TGF-β/MAPK signaling pathway, can significantly promote glioma cell proliferation and migration." (PMID 31719831, 2019). "This includes an overexpression of tenascin-C at the invasive front, increasing motility of glioma cells via interactions with β1 or αvβ3 integrins, probably via an activation of FAK and inhibition of RhoA." (PMID 31003495, 2019). "Taken together, these data firmly implicate GNA13 and downstream RhoA signaling, along with potentially other ATRX-responsive genes, in the process of ATRX-dependent glioma cell migration." (PMID 29535300, 2018). "Levels of RhoA guanosine triphosphate (GTP) were increased and RhoA guanosine diphosphate (GDP) amount was reduced, indicating that RhoA/ROCK2 was activated in TMZ-R glioma cells." (PMID 29416017, 2018). "In summary, we have identified RhoGDIα/RhoA/ROCK1 pathway as a regulator of GSCs maintenance, and RhoGDIα is a potential molecular target of GSCs for future therapy of glioma." (PMID 27557508, 2016). "Seven Rho GTPases (RND1, RND3, RAC3, RHOA, RAC2, RAC1 and RHOC) showed a significantly greater connectivity in grade IV glioma and seven (CHP, RHOD, RHOF, RHOB, RHOQ, RND2, RHOBTB3) showed greater connectivity in grade II glioma." (PMID 26132659, 2015).
glioma (continued). "This includes effects on cell invasion (RAC1, RAC2, RAC3, RHOA, RHOC), focal adhesion formation (RHOA), stemness of glioma precursor cells (RAC1), cell proliferation (RAC1, RND3) and cell cycle (RND3)." (PMID 26132659, 2015). "Treatment of glioma cells with MAZ51 resulted in increased levels of phosphorylated GSK3β through the activation of Akt, as well as increased levels of active RhoA." (PMID 25268128, 2014). "LRRC4/NGL-2 overexpression inhibited glioma cell growth and invasion through miR-185-mediated CDC42 and RhoA direct regulation and VEGFA indirect regulation." (PMID 25526788, 2014). "This suggests the presence of a feedback loop of ROCK expression on RhoA since ROCK1 and ROCK2 are downstream effectors of RhoA in glioma cells." (PMID 24170433, 2014). "Functional evidence for the role of RhoA has been demonstrated under the inhibition of the RhoA effector ROCK, which led to activation of Rac1 in glioma cells and promoted invasion." (PMID 24109588, 2013). "To precisely unravel the pathways that were related to the function of KIF4A in cytoskeletal remodeling of glioma, we hypnosis that whether KIF4A regulated F-actin through RhoA or Rac1/Cdc42." (PMID 36606197, 2022). "Moreover, in glioma cells, s-μg inhibited FAK, reduced RhoA/Rock signalling and Nek2 expression, and attenuated glioma viability and migration." (PMID 35052703, 2021). "A recently identified RSK–LARG–ROCK pathway suggests that in glioma cells, RSK may also inhibit MYPT1 and promote motility through phosphorylation and activation of the LARG RhoGEF, which increases RhoA activation." (PMID 31138649, 2019). "The RhoA protein expression level in HCC ranked second, next to that in glioma, in all common tumor types, which indicated that the RhoA protein, rather than the gene, may promote liver tumorigenesis as an essential functional element." (PMID 31339860, 2019). "In glioma cells, RHO GTPases including RHOA and RAC regulate cytoskeletal rearrangements resulting in ameboid and mesenchymal cell motility and have been shown to promote migration and growth of glioma cells in vitro and ex vivo." (PMID 31467533, 2019). "Also, we found that PINCH1, RhoA and MMP13 play a crucial role being regulated by the RSU-1/GDF15 interplay leading to affection of the final invasive phenotype of glioma cells." (PMID 31412547, 2019). "In glioma cells, CD271 plays a critical role in actin fiber formation via a RhoA-dependent pathway." (PMID 27469492, 2016). "This interaction may participate, in addition to its known modulatory activity on RhoA activity, to the biological effects triggered by RND3 in glioma cells." (PMID 26132659, 2015). "Nine novel functional miRNAs (hsa-miR-129, -136, -145, -155, -181b, -342-5p, -342-3p, -376a/b) in GBM cell lines were validated for their importance in glioma cell growth, and similar effects for six target genes (ROCK1, RHOA, MET, CSF1R, EIF2AK1, FGF7) of these miRNAs were shown functionally." (PMID 23577178, 2013). "Since we observed that SOX2 depletion led to a decrease in cyclinD1 expression we suggest that the same mechanism might be involved in the increased RhoA/ROCK2 signaling in U343-MG and U373-MG glioma cells." (PMID 22070920, 2011). "Moreover, glioma cells have shown to shift from a slow, random migration mode (exhibiting lower Rac1 and CDC42 activities), when crossing the parenchyma, to a fast migration course (exhibiting higher RhoA activity) on the linear blood vessels." (PMID 31075964, 2019). "In addition, previous studies proved that δ-catenin has an influence in other small GTPases, such as Cdc42 and RhoA, which was not investigated in glioma cell lines." (PMID 22151302, 2011). "Interestingly, RhoA/ROCK pathway is activated by TRPC6 in other tissues such as the kidney, suggesting that this relation between TRPC6 and RhoA/ROCK might also play a role in glioma progression." (PMID 33240883, 2020).
glioma (continued). "Studies of cell survival in glioma show that netrin acts as a pro-survival ligand for UNC5B in glioma as well, while also promoting invasion and angiogenesis of GBM cells by activating RhoA, cathepsin B, cAMP response element binding protein, and Notch signaling." (PMID 34359681, 2021).
osteosarcoma (57 papers, 2005 to 2025). A usually aggressive malignant bone-forming mesenchymal neoplasm, predominantly affecting adolescents and young adults. "The RhoA‐ROCK‐LIMK2 signaling pathway contributes to osteosarcoma cell migration and is implicated in cellular autophagy and apoptosis." (PMID 38800967, 2024). "Statin drugs induce apoptosis in osteosarcoma cells by altering the localization of RhoA, causing its relocation from the cell membrane to the cytoplasm and leading to RhoA isoprenylation." (PMID 38800967, 2024). "As well, p190A, a RhoGAP for RhoA has been implicated as an oncogenic GAP in osteosarcoma, colorectal, lung and breast cancer." (PMID 34493786, 2021). "Studies have shown that BMPR2 is highly expressed in most osteosarcoma tissues, is associated with overall survival in osteosarcoma patients, and promotes invasion and metastasis via the RhoA-ROCK-LIMK2 pathway in human osteosarcoma cells." (PMID 34903128, 2021). "Expression of recombinant Arhgap28-V5 in human osteosarcoma SaOS-2 cells caused a reduction in the basal level of RhoA activation and disruption of actin stress fibers." (PMID 25211221, 2014). "ARHGEF3 downregulation may be associated with invasion, metastasis, and proliferation in osteosarcoma because this gene specifically activates RHOA and RHOB, which play a role in bone cell biology." (PMID 37315301, 2023). "Specifically, RhoA’s activation has been associated with osteosarcoma metastasis to the lungs." (PMID 38140058, 2023). "LAPTM4B was found to promote RhoA protein stability in osteosarcoma (OS) cells by inhibiting RhoA ubiquitination and RhoA proteasome degradation, which in turn was important in stress fiber regulation." (PMID 40231269, 2025). "Mechanistically, PD-L2 is able to activate RhoA-ROCK-LIMK2 and autophagy pathways underlying osteosarcoma invasion and metastasis, supporting the biologic relevance of PD-L2 with cancer progression." (PMID 39284838, 2024). "By inhibiting RhoA‐GTPase activity, statin drugs block the p42/p44‐MAPKs survival pathway, accelerating apoptosis in osteosarcoma cells." (PMID 38800967, 2024). "The in vivo and in vitro lentivirus-mediated siRNA reduction of MALAT1 expression decreases in PCNA, MMP-9, p-PI3K, and RhoA/ROCKs expression, which then attenuates the growth, invasion, and dissemination of osteosarcoma cells." (PMID 39015175, 2024). "The epidermal growth factor (EGF) also promotes MG63 osteosarcoma cell migration and invasion, as well as stress fibre formation via RhoA activation." (PMID 36899941, 2023). "In a mouse experiment, EVs were found to carry the Rab22a-NeoF1 fusion protein to promote osteosarcoma cell metastasis to the lung via PYK2 activation of RhoA in donor cells in osteosarcoma." (PMID 38037077, 2023). "Consistently, PD-L2 expression induced EMT by inactivating the RhoA-ROCK-LIMK2 axis in osteosarcoma." (PMID 36522474, 2023). "Fasudil is reported to inhibit RhoA signalling in many diseases such as cardiomyopathy and osteosarcoma." (PMID 34245091, 2021). "Taken together, these results suggest that simvastatin alters RhoA protein prenylation through depletion of the mevalonate intermediate geranylgeranyl pyrophosphate (GGPP) in our murine osteosarcoma cells." (PMID 34831022, 2021). "We previously demonstrated that lipophilic statins (atorvastatin, simvastatin, or cerivastatin) trigger caspases-dependent apoptosis in osteosarcoma cells and reduce cell invasiveness through inhibition of a RhoA GTPase-JNK-MMP2 cascade." (PMID 34831022, 2021). "Then, through coimmunoprecipitation and other techniques, Rab22a-NeoF1 was uncovered to promote osteosarcoma lung metastasis by activating RhoA." (PMID 32839478, 2020). "A previous study suggested that PD-L2 knockdown inhibited osteosarcoma pulmonary metastasis by the RhoA-ROCK-LIMK2 pathway; thus, we further investigated the effect of apatinib on the RhoA-ROCK-LIMK2 pathway." (PMID 33014879, 2020).
osteosarcoma (continued). "A recent study implicates MYO9B in the regulation of constitutive activity of RhoA to generate self-limiting cellular contraction patterns in the human osteosarcoma cell line, U2OS83." (PMID 32807784, 2020). "A previous study indicated that PD-L2 knockdown inhibits the ability of osteosarcoma cells to metastasize by the RhoA-ROCK-LIMK2 signaling pathway; thus, we further investigated the effect of VEGFR2 inhibition on RhoA-ROCK-LIMK2 signaling." (PMID 33014879, 2020). "Rab22a-NeoF1 is acetylated at K7; such an acetylation facilitates its interaction with SmgGDS607 and leads to the excessive activation of RhoA GTPase to be transferred on membrane, which in turn promotes metastasis in osteosarcoma." (PMID 32685017, 2020). "In osteosarcoma, our observation that RhoA is suppressed after depleting Skp2 is consistent with previous reports." (PMID 30250282, 2018). "Since the RhoA GTPase plays a crucial role in the invasiveness and metastasis of multiple cancers, it is likely that FKA or Skp2 knockdown blocks RhoA, leading to inhibition of invasiveness and lung metastasis in osteosarcoma." (PMID 30250282, 2018). "In this study, overexpression of constitute active RhoA rescues Wnt5a-induced cell migration blocked by shRNA or siRNA against ROR2 in osteosarcoma cells." (PMID 29213214, 2017). "We have reported that the phosphatidylinositol-3 kinase (PI3K)/Akt/RhoA signaling pathway mediates Wnt5a-induced cell migration of osteosarcoma cells." (PMID 29213214, 2017). "Here, we demonstrates that ROR2 receptor activates PI3K/Akt/RhoA signaling and mediates Wnt5a-induced the migration of osteosarcoma cells." (PMID 29213214, 2017). "We evaluated the activations of RhoA, Rac1 and Cdc42 in osteosarcoma MG-63 and U2OS cells with small G-protein activation assay." (PMID 28289332, 2017). "We present the evidence here that RhoA mediates Wnt5a-induced osteosarcoma cell migration via PI3Kα, Akt1 and Akt2 isoforms." (PMID 28289332, 2017). "Taken together, we demonstrate that ROR2 receptor responding to Wnt5a ligand activates PI3K/Akt/RhoA signaling and promotes the migration of osteosarcoma cells." (PMID 29213214, 2017). "The effect of knockdown of ARHGEF10, RhoA or KIF3B was also examined in osteosarcoma U2OS cells arrested in S phase by aphidicolin treatment." (PMID 19635168, 2009). "The RhoA‐ROCK‐LIMK2 signal pathway is important for the osteosarcoma migration and related to PCD." (PMID 38800967, 2024). "Ultimately, these findings, obtained through genetic enhancement of autophagy combined with treatment with a cytoskeleton signaling pathway inhibitor, indicated that anlotinib-induced autophagy promoted the metastasis of human osteosarcoma cells via RhoA-ROCK-LIMK2 signaling and EMT." (PMID 38381883, 2024). "Herein, we found that both Siglec-15 silencing and Beclin-1 depletion could decrease RhoA activation and lessen the formation of lamellipodial protrusions in the submembranous area in osteosarcoma cells." (PMID 35842729, 2022). "In osteosarcoma cells, RhoA was shown to activate the p42/p44 MAPKs/Bcl-2 survival pathway, which may be inhibited by lipophilic statins, inducing caspase-dependent apoptosis." (PMID 33546351, 2021). "A parallel alignment of cells to strain has previously been described as dependent on the activation of the GTPase RhoA, and associated with a lack of stress fibers in endothelial and osteosarcoma cells." (PMID 34630042, 2021). "The K7R mutant of Rab22a-NeoF1 lacks its binding to SmgGDS607 and subsequently lost its promoting functions, such as activation of RhoA, cell migration, invasion and lung metastasis in osteosarcoma in vitro and in vivo, which are also diminished by p300/CBP inhibitor C646." (PMID 32685017, 2020).